CD93 (CD93 molecule)
Diseases named in the same sentence as CD93 in open-access papers (continued):
Sharing a sentence is not in itself a finding about the gene and the disease.
cancer (continued). "In this same CD93-specific screening investigation, increased CD93 expression correlated with higher number of infiltrating T cells in some cancers but also higher immunosuppressive macrophage presence." (PMID 38468017, 2024). "Although CD93 has been wildly reported to play a critical role in many types of cancer, there are few studies to reveal the value of CD93 in LIHC." (PMID 37483608, 2023). "We found that the functions of CD93 in different cancers are mainly related to Insulin like growth factor binding protein 7 Gene (IGFBP7)/CD93 pathway via STRING, GeneMania and functional enrichment analyses." (PMID 37483608, 2023). "There were a lot of studies that reported that CD93 was involved in the regulation of the immune response in different cancers." (PMID 37483608, 2023). "Functional analysis showed a correlation among CD93 and cancer promotion, angiogenesis and inflammation." (PMID 37443812, 2023). "The researchers have reported that CD93 took part in the control of endothelial cell function through the cooperation between CD93 and dystroglycan, a laminin-binding protein, in malignant tumors." (PMID 37483608, 2023). "Through high-throughput bioinformatics analysis, the present work illustrated a comprehensive workflow for STAD and thoroughly elucidated the role of CD93 in cancer." (PMID 36761750, 2023). "CD93, a transmembrane protein, has been widely reported to play an important role in different types of diseases, including many types of cancer by mainly functioning in extracellular matrix formation and vascular maturation." (PMID 37483608, 2023). "There are numerous studies that have found that CD93 plays a critical role in many diseases, including allergic asthma, diabetic wound healing, and many types of cancer." (PMID 37483608, 2023). "Data showed that the many immune checkpoints positively correlate with CD93 expression in many cancers, particularly NRP1, LAIR1, VSIR, and CD86." (PMID 36389798, 2022). "In our study, CD93 expression was enormously related to MMR genes in almost all cancers we analyzed." (PMID 35242761, 2022). "More recently, numbers of works support the importance of CD93 expression in immune response during the development of cancers via alterations in immune cell phenotype, function, and infiltration." (PMID 35242761, 2022). "The survival difference between CD93 mutants and WT, CNV of CD93 and survival, the correlation between CD93 methylation and mRNA levels, and the survival difference between CD93 low and high methylation in pan-cancer were analyzed." (PMID 36389798, 2022). "In this study, we demonstrate that the differential expressions of CD93 in cancers help with prognosis estimation, the exploration and research of its mechanism, prediction of therapeutic effects, and the development of new treatments." (PMID 35242761, 2022). "In accordance with previous results on the role of CD93 in regulating immune infiltrates, we observed that CD93 was enriched in mononuclear/macrophage subsets, neutrophils, and B cells in some types of cancer." (PMID 35242761, 2022). "In our paper, we observed the mRNA expression of CD93 in 38 cancer cell lines, 31 cancer samples, and counterparts based on public databases." (PMID 36389798, 2022). "The expression of CD93 in tumors seems to make varying contributions among different types of cancer." (PMID 35242761, 2022). "Our data showed that CD93 expression was positively correlated with almost all immune-related genes in nearly all cancers." (PMID 35242761, 2022). "To specifically address the function of CD93 in human pan-cancer, we performed enrichment analysis on CD93 and found a link between it and promoting cancers and inflammation." (PMID 35242761, 2022). "Function analysis on CD93 revealed a link between itself and promoting cancers, inflammation, and angiogenesis." (PMID 35242761, 2022).
cancer (continued). "CD93 levels and co-expression of CD93 on cancer and stromal cells were detected using public databases and multiple immunofluorescence staining." (PMID 36389798, 2022). "Given that the molecular characteristics of CD93 in pan-cancer remain unexplored, we performed large-scale single-cell and bulk sequencing analysis to identify the prognostic value and immune features of CD93 in these cancers." (PMID 36389798, 2022). "To further validate the link between CD93 expression and other cancer-related biological functions in pan-cancer, we analyzed additional two biological roles of CD93 in various human tumors including autophagy, EMT, TGFB1, and Wnt pathway." (PMID 35242761, 2022). "CD93 mRNA and protein levels differed significantly between cancer samples and adjacent control tissues in multiply cancer types." (PMID 36389798, 2022). "We found that CD93 was extremely enriched in endothelial cells and mononuclear/macrophage subsets among all of these cancers." (PMID 35242761, 2022). "Noticeably, CD93 was essentially enriched in CAFs, endothelial cells, and hematopoietic stem cells among these cancers." (PMID 35242761, 2022). "CD93 blockade was proved to be effective in antiangiogenic therapy and vascular normalization of cancers." (PMID 36006582, 2022). "In this project, we comprehensively analyzed the prognostic value and immune profile of CD93 in pan-cancer using large-scale single-cell and bulk sequencing analysis." (PMID 36389798, 2022). "We believe that this study lays a solid foundation for further exploration of the value of CD93 in cancer prognostic biomarkers and immunotherapy in the future." (PMID 35265666, 2021). "We obtained the RNA sequences and clinical data from The Cancer Genome Atlas (TCGA) and UCSC Xena, respectively, and analyzed the prognostic value of CD93 in pan-cancer." (PMID 35265666, 2021). "For example, RT-PCR, Western blot, IHC, and other experimental methods can be used to verify the expression of CD93 in pan-cancer." (PMID 35265666, 2021). "The mRNA and protein levels of CD93 in multiple cancer types were also explored via the HPA dataset." (PMID 35265666, 2021). "The results showed significant differences in the expression of CD93 between cancer tissues and normal tissues." (PMID 35265666, 2021). "The development of immune checkpoint inhibitors against CD93 is expected to play an important role in the immunotherapy of malignant tumors." (PMID 35265666, 2021). "Based on the TISIDB database, we further analyzed the relationship between the expression of CD93 and the immune subtypes of different cancer species." (PMID 35265666, 2021). "Furthermore, reduced CD93 expression has been correlated with improved prognosis and enhanced response to immunotherapy in cancer patients." (PMID 40943530, 2025). "Furthermore, the function of CD93 in different cancers was primarily related to the IGFBP7/CD93 signaling pathway." (PMID 40943530, 2025). "In addition, CD93 serves as a stable prognostic biomarker across most cancer types, with the exception of ACC, BRCA, CHOL, diffuse large B-cell lymphoma (DLBC), PAAD, PRAD, SKCM, and UCS." (PMID 40943530, 2025). "CD93 expression correlates strongly with the presence of monocyte/macrophage lineages and neutrophils while showing a negative correlation with Th1, MDSCs, NK cells, and T follicular helper cells in nearly all cancers." (PMID 40055311, 2025). "The development of humanized monoclonal antibodies or other therapeutics targeting CD93 may offer new treatment options for patients with inflammatory disorders, cardiovascular diseases, and various cancers, potentially leading to improved clinical outcomes." (PMID 40943530, 2025). "S100A8 and S100A9/Cd93 were major communication axes within Cancer-B1/2/3-TME." (PMID 39695088, 2024). "Moreover, CD93 expression was associated with poor prognosis, immune cell infiltration and high TNM stage in many cancer types." (PMID 37443812, 2023).
cancer (continued). "Additionally, considering that CD93 has been implicated to play roles in the etiology of multiple diseases and therefore multiple pathways that have implications outside of cancer, this makes CD93 a unique and enticing target." (PMID 36761750, 2023). "Our finding suggested that CD93 may be a promising target for immunotherapy of STAD or other types of cancer." (PMID 36761750, 2023). "The researcher also validated that the CD93 pathway in the TME may contribute to cancer resistance to anti-PD therapy in humans." (PMID 36761750, 2023). "Notably, CD93 expression significantly correlated with these scores (immune, stromal, and estimate) in almost all cancers." (PMID 36389798, 2022). "Therefore, we further investigated on the role of CD93 in immune-cell infiltration levels in 33 types of cancer." (PMID 35242761, 2022). "The Kaplan-Meier (KM) analysis identified the predictive role of CD93 in these cancer types." (PMID 36389798, 2022). "Moreover, large-scale single-cell sequencing analysis demonstrated that macrophages, astrocytes, CAFs, T cells, B cells, endothelial cells, neutrophils, and cancer cells are the primary cells that expressed CD93 in the TME." (PMID 36389798, 2022). "However, despite the recent attention CD93 has received, its role in pan-cancer has remained unexplored prior to this investigation." (PMID 35242761, 2022). "Furthermore, the immunotherapy effectiveness and sensitive drugs targeting CD93 in these cancers were predicted." (PMID 36389798, 2022). "Further explorations of the mechanisms of CD93 in the immune system may help improve cancer therapy methods." (PMID 35242761, 2022). "It is conceivable to expect that the exploration of CD93 may therefore lead to major breakthroughs in the treatment of cancer, bringing great hope to those patients who have troubles with cancer diseases." (PMID 35242761, 2022). "Now we have established that CD93 is expressed differently in different cancers." (PMID 35242761, 2022). "Unlike other cancers, there was a more negative association between CD93 and immunostimulatory genes in TGCT." (PMID 35242761, 2022). "In addition, CD93 can serve as a stable prognostic biomarker in almost all cancers except ACC, BRCA, CHOL, DLBC, PAAD, PRAD, SKCM, and UCS." (PMID 36389798, 2022). "Inhibition of the CD93 pathway may be a novel and promising strategy for immunotherapy in human cancer." (PMID 35242761, 2022). "Therefore, in this paper, we systematically checked the prognostic and immune role of CD93 in pan-cancer based on public databases like TCGA, CCLE, and GTEX." (PMID 36389798, 2022). "Consistent with our data, CD93 was reported to be involved in apoptosis and inflammation and had a suggested role in angiogenesis, and thus involved in the development and dissemination of cancer." (PMID 35242761, 2022). "Based on the cBioPortal database, we analyzed the genetic alteration of CD93 in pan-cancer." (PMID 35265666, 2021). "Then, we used the TISIDB database to explore whether CD93 was correlated with the immune subtype in multiple cancer types." (PMID 35265666, 2021). "Besides, this research revealed the relationship between CD93 expression and immune cell infiltration and immune biomarkers, thus providing valuable insight into the role of CD93 in cancer immunotherapy." (PMID 35265666, 2021). "Both CD93 and Moesin (MSN) are involved in apoptosis and retained in the sensitivity profile in line with theory and ANP32E that removes histone H2A.Z, a splice variant of a histone, is involved in several cancer types." (PMID 29566065, 2018). "Cluster of differentiation 93 (CD93) is involved in apoptosis and inflammation and has a suggested role in angiogenesis, and all of which are involved in the development and dissemination of cancer." (PMID 26008729, 2015).
cancer (continued). "Furthermore, in multiple cancer types, CD93 expression positively correlates with the expression of various immune checkpoint molecules, including CD86, leukocyte-associated immunoglobulin-like receptor 1 (LAIR1), V-set immunoregulatory receptor (VSIR), and neuropilin 1 (NRP1)." (PMID 40943530, 2025). "Therefore, CD93 plays a pivotal role in the regulation of carcinogenic properties, demonstrating its potential as a biomarker for predicting the prognosis and immune infiltration of different cancer types." (PMID 38999940, 2024). "Thus, the blockade of IGFBP7/CD93 interaction can be a novel approach to favor cancer treatment." (PMID 37443812, 2023). "Moreover, low CD93 expression showed an improved cancer outcome and immunotherapy response." (PMID 37443812, 2023). "We first evaluated the expression levels and prognostic significance of CD93 in 33 types of cancers to explore its role across cancers and whether it can serve as a prognostic biomarker, which is a meaningful study to facilitate the translation of basic science to clinical studies." (PMID 35242761, 2022). "Thus, the neutralization of CD93 in combination with other drugs or blocking agents could be revealed instrumental in antiangiogenic treatment of cancer." (PMID 24809468, 2014). "Multiple experiments abroad have been conducted to develop CD93-related drugs, including DCBY 02, WO2024115637, CD34-Derived Allogeneic Dendritic Cell Cancer Vaccine, and DCSZ11." (PMID 40943530, 2025). "We found that C3AR1 expression is higher in GBM as compared with all other cancers analyzed in TCGA, whereas Complement Receptor 1 (CR1), CR2, C1qR1 (CD93), and C5AR1 were expressed at varying levels." (PMID 39172519, 2024). "Therefore, since CD93 can regulate immune responses and immune cell infiltration, it can significantly regulate the malignant properties of various cancer types and it could have a potential value as a biomarker for determining the prognosis and immune infiltration in various type of cancers." (PMID 37443812, 2023). "Thus, CD93 could be a good prognostic marker and molecular target in many types of cancer." (PMID 37443812, 2023). "We also analyzed the correlations between CD93 and B cells, CD8 + T cells, CD4 + T cells, macrophages, neutrophils, and dendritic cells in 32 types of cancer via the TIMER database." (PMID 35242761, 2022). "Multiple immunofluorescence staining displayed the relationship between CD93 expression and CD8, CD68, and CD163 in these cancers." (PMID 36389798, 2022). "As shown in this study, the expression of CD93 is positively connected with stromal scores, immune scores, as well as ESTIMATE scores in the overwhelming majority of cancers but TGCT, THCA, THYM, and UCEC." (PMID 35242761, 2022). "Their results proved that blockade of the CD93 pathway can sensitize tumors to ICB therapy and facilitate cancer immunotherapy." (PMID 35242761, 2022). "To link them to the generation of B-MF, we FACS-purified CD93+ and CD93− BMBP from the spleen of mice with 4T1.2 cancer and naïve mice and cultured these cells in 4T1.2-CM." (PMID 36104343, 2022). "Our data showed that the expression of CD93 was positively connected with StromalScores, ImmuneScores, as well as ESTIMATE scores in human pan-cancer." (PMID 35242761, 2022). "Four members compose the group XIV of CTLDcps: CD93, Clec14A, CD248, and Thrombomodulin, which have been studied extensively in human and mouse in the contexts of angiogenesis and cancer biology." (PMID 35659564, 2022). "In mice with 4T1 cancer, CSF1R+CD93+CD19+ BMBP were markedly reduced in BM but increased in the spleen, consistent with their cancer-induced emigration from BM." (PMID 36104343, 2022). "Namely, CLEC14A, CD93, endoglin, and ANTXR1 (alias TEM8) have shown to be overexpressed in several cancers." (PMID 34770976, 2021).
cancer (continued). "Taken together, our data identify CD93 as a key regulator of endothelial barrier function in tumors through modulating VEGFR2 function, which has important implications for its therapeutic targeting in cancer." (PMID 38441970, 2024). "CD93 and FGL2 were recently highlighted as promising CAR‐T cell targets in AML or other cancers." (PMID 39054581, 2024). "Given that TMB status is gradually regarded as one of the promising pan-cancer biomarkers for forecasting ICB therapeutic effect, which has already been approved by the FDA, we checked the correlation between CD93 expression and TMB across cancers." (PMID 35242761, 2022). "The group XIV of C-type lectin domain-containing proteins (CTLDcps) is one of the seventeen groups of CTLDcps discovered in mammals and composed by four members: CD93, Clec14A, CD248 and Thrombomodulin, which have shown to be important players in cancer and vascular biology." (PMID 35659564, 2022). "In addition, recent papers have shown that CD93 is a prognostic marker for many malignant cancers and is involved in immune responses in the TME during cancer immunization." (PMID 36389798, 2022). "Thus, comprehensive CD93 analyses based on prognostic, TME, immunological effects, and therapeutic effects across all cancer types are acquired." (PMID 35242761, 2022). "In all analyzed cancers, ENTPD had the strongest correlation with CD93." (PMID 35242761, 2022). "Noticeably, our results mediated a strong positive contact between CD93 and CAFs, endothelial cells, myeloid dendritic cells, hematopoietic stem cells, mononuclear/macrophage subsets, and neutrophils while a negative correlation with Th1, MDSC, NK, and T-cell follicular helper in almost all cancers." (PMID 35242761, 2022). "Additionally, CD93 also correlated with TMB and MSI in certain types of cancer." (PMID 35242761, 2022). "FACS staining confirmed that Pax5 was markedly decreased in BM CD93+ BMBP, particularly in CSF1R+ but not CSF1R− subsets, from mice with 4T1.2 or Mogp cancers." (PMID 36104343, 2022). "Compared with naïve mice, the total number of CD93+ BMBP was markedly decreased in BM but increased in the spleen as well as present in the tumors of mice with 4T1.2 and Mogp cancers (b and not depicted)." (PMID 36104343, 2022).